MYO6 (myosin VI)
Diseases named in the same sentence as MYO6 in open-access papers (continued):
Sharing a sentence is not in itself a finding about the gene and the disease.
hearing loss (continued). "Furthermore, genetic testing identified novel MYO6 variants, c.[2377T>G; 2382G>T] p.[Trp793Gly; Lys794Asn], positioned in a cis pattern, as plausible pathogenic contributors to early-onset hearing loss characterized by a severe and progressive course." (PMID 38274113, 2023). "MYO6 is involved in various physiological processes in vivo, and its expression has been reported to be increased in humans and mice in different diseases, including cancer and hearing loss." (PMID 37817158, 2023). "In summary, using a large cohort, we could obtain a more complete pictures of the mutational spectrum, frequency of mutations, and characteristic clinical features of patients suffering from hearing loss caused by MYO6 variants." (PMID 32143290, 2020). "Variants in myosin VI (MYO6) have been identified in AD and recessive hearing loss." (PMID 32066420, 2020). "Finally, the likely pathogenic novel MYO6 (c.494T > G/p.(Leu165Arg)) variant was found in patient 41268, referred to as AD non-syndromic hearing loss." (PMID 33297549, 2020). "Most MYO6-associated hearing loss reported in previous papers showed progressive hearing loss." (PMID 32143290, 2020). "Indeed, an autosomal semi-dominant inheritance mode has been previously reported in MYO6-related hearing loss." (PMID 32143290, 2020). "The frequency of MYO6-associated hearing loss was 2.40% in the Japanese AD hearing loss patients." (PMID 32143290, 2020). "Thus, the prevalence of MYO6-associated hearing loss was 2.40% (32/1336) of Japanese autosomal dominant sensorineural hearing loss (ADSNHL) patients and 0.41% (33/8074) of all inheritance modes of Japanese hearing loss patients." (PMID 32143290, 2020). "Homozygous mutations of MYO6 result in nonsyndromic profound congenital hearing loss, DFNB37." (PMID 28832620, 2017). "Two non-syndromic hearing loss (NSHL) genes (BDP1 and MYO6) were reported in two separate families in South Africa, suggesting a possible phenotypic expansion." (PMID 41516007, 2025). "Among these elements, we identified six potential variants in cis-regulatory elements associated with hearing loss genes, CDH23, OTOF, MYO6, COL4A4 and WHRN." (PMID 40164689, 2025). "TRIOBP, MYO6, and COL11A2 were found in both clinical gene sets (otoscope and clingen), and common variant studies of hearing loss (GWAS)." (PMID 38943082, 2024). "Two genes encoding conventional myosins, MYH9 and MYH14, and four genes encoding unconventional myosins, MYO3A, MYO6, MYO7A and MYO15A, are associated with nonsyndromic hereditary hearing loss in human." (PMID 38562617, 2024). "HL associated with the MYO6, TECTA, and COCH genes was identified in patients with mild hearing loss." (PMID 38790200, 2024). "Myosin genes are known to be responsible for 10 types of syndromic as well as non‐syndromic hearing loss (MYO7A, DFNA11/DFNB2/USH1B; MYH9, DFNA17; MYH14, DFNA4; MYO6, DFNA22/DFNB37, MYO3A, DFNB30; MYO15A, DFNB3)." (PMID 32027099, 2020). "Compared to the prelingual group, many genes with autosomal dominant inheritance, such as MYO7A, ACTG1, DFNA5, MYO6, and CRYM, as well as mitochondrial genes reported to cause progressive hearing loss, were found to be involved." (PMID 32027099, 2020). "In addition, variants in two non-syndromic hearing loss (NSHL) genes (BDP1 and MYO6) were reported in two independent South African families with WS features, suggesting a possible phenotypic expansion." (PMID 41516007, 2025). "Furthermore, earlier research has suggested that MYO6-related hearing impairment initially impacts high frequencies before progressing to middle and low frequencies." (PMID 38274113, 2023). "We concluded that the POU4F3 variations might regulate Wnt, Notch, and/or BMP pathways, specifically leading to the misregulation of BMP2, MYO6, and AHI1 in the pathogenesis of hearing loss." (PMID 37537203, 2023).
hearing loss (continued). "In addition, labeling of the cochlea with a combination of anti-prestin, anti-neurofilament, anti-myosin VI and/or phalloidin and DAPI will be useful for detecting potential recent cases of noise-induced hearing loss in stranded cetaceans." (PMID 32851016, 2020). "The mechanism we present here, where GRXCR2 restricts taperin from entering the stereocilia shaft, may also explain the morphological defects and hearing loss caused by mutations of CLIC5, radixin, PTPRQ, MYO6, Fam65b, or other components located at the basal region of stereocilia." (PMID 30380417, 2018).
prostate carcinoma (22 papers, 2009 to 2025). A carcinoma that arises from epithelial cells of the prostate gland. "Here, the loss of miR-143 and miR-145 targeting myosin VI (MYO6) was suggested as a diagnostic marker for prostate carcinoma." (PMID 28621736, 2017). "Furthermore, MYO6 overexpression correlates with clinically aggressive behaviour in both ovarian and prostate carcinomas, which is believed to be linked to the role of MYO6 in cellular migration." (PMID 36551317, 2022). "Furthermore, MYO6 is strongly associated with Gleason score in prostate cancer." (PMID 38774081, 2024). "Consistent with this, structured illumination microscopy in prostate cancer cells revealed signal-dependent nuclear enrichment of myosin VI, which localized in close proximity to AR as well as RNA Pol-II clusters and the actin nucleator DAAM2." (PMID 41443423, 2025). "While our data suggests miR-145-5p regulation of MYO6 exerts a similar effect in prostate cancer cells, its effect on other targets is also important to acknowledge." (PMID 38673886, 2024). "MYO6 was selected for further analysis due to its previously established link with prostate cancer which we also observed in the functional enrichment analysis performed here." (PMID 38673886, 2024). "Taken together, these data provide evidence that MYO6 is a direct target of miR-145-5p in prostate cancer." (PMID 38673886, 2024). "This is the first report demonstrating that downregulation of miR-145-5p can promote prostate cancer development through targeting MYO6 and regulating EMT." (PMID 38673886, 2024). "MYO6, an EMT-associated gene, was identified and validated as a novel target of miR-145-5p in prostate cancer cells." (PMID 38673886, 2024). "PSA colocalises with motor protein myosin VI in transferrin-positive recycling endosomes in prostate cancer cells, and its secretion was reduced when myosin VI was knocked down, highlighting a critical role for endosome transport in modulating PSA secretion." (PMID 39796673, 2024). "Myosin VI (MYO6), serving as a sensitive biomarker, was highly expressed in the Golgi apparatus of prostate cancer cells." (PMID 36846347, 2023). "In prostate cancer, expression of myosin VI was increased in medium grade cancer than the aggressive ones." (PMID 33171868, 2020). "MYO6 is overexpressed in lung cancer, breast cancer, hepatocellular carcinoma, ovarian cancer, and prostate cancer." (PMID 32670437, 2020). "Recently, it was found that both GOLPH2 and myosin VI were overexpressed in prostate cancer, where immunofluorescence showed a more obvious Golgi staining of these two proteins in cancer cells than in the adjoining normal epithelium." (PMID 27121062, 2016). "MYO6 (myosin VI) is critical in maintaining the malignant properties of the majority of human prostate cancers diagnosed today." (PMID 19463170, 2009). "Regarding potential therapeutic applications, our data also show that restoring miR-145-5p levels in prostate cancer cells, thereby reducing MYO6 levels, could be a viable strategy to suppress EMT and inhibit cell growth." (PMID 38673886, 2024). "Transient overexpression of miR-145-5p in RWPE1, DU145 and PC3 prostate cancer cell lines consistently led to decreased MYO6 mRNA and protein levels, which was validated by a significant negative correlation between miR-145-5p and MYO6 expression in TCGA PRAD samples." (PMID 38673886, 2024). "In summary, this is the first study to report that miR-145-5p may inhibit EMT by targeting MYO6 in prostate cancer cells." (PMID 38673886, 2024). "MYO6 upregulation drives metastasis and progression in breast, gastric, and prostate cancer." (PMID 37240349, 2023). "In prostate cancer tissues, MYO6 and GOLM1 are known to co-locate at the golgi." (PMID 34680291, 2021). "Knocking out MYO6 in prostate cancer cells leads to in vitro migration and defects in growth." (PMID 32670437, 2020). "MYO6 has been indicated to promote cell proliferation in lung cancer and prostate cancer." (PMID 32993655, 2020).
prostate carcinoma (continued). "Knockdown of Myo6 in prostate cancer cell line led to trafficking defects, which may affect normal cell migration." (PMID 33171868, 2020). "Another similar relationship between myosin VI and the spreading of cancer cells has also been observed in prostate cancer, where the analysis of the detailed mechanisms suggest possible myosin VI involvement in the maintenance of cell polarity, cell-cell adhesion and material transportation." (PMID 27121062, 2016). "Therefore, it would be interesting to determine if this missense SNP generates a form of LMTK2 with differential binding capacity for myosin VI, ultimately affecting intracellular trafficking and the endosomal secretory pathway in prostate cancers." (PMID 25658610, 2015). "In prostate cancer cells, MYO6 is mainly associated with recovered endosomes, not endocytic vesicles or Golgi apparatus, which may be due to lower levels of Dab2 and optineurin in these cells." (PMID 32670437, 2020). "MYO6 is highly expressed in prostate cancer, ovarian cancer, gastric cancer and oral squamous cell carcinoma and can promote proliferation and migration through the lncRNA UCA1/miR-143/MYO6 axis." (PMID 41262242, 2025). "Interestingly, myosin VI is overexpressed in prostate cancer, with the highest expression in high-grade prostate cancers, suggesting that the motor proteins regulating endosome transport and secretion of kallikrein biomarkers may help inform on advanced prostate cancer." (PMID 39796673, 2024). "Future work will involve determining if AA prostate cancer tissues exhibit progression and metastatic potential via activated Akt through RTK recycling mechanisms promoted by MYO6 and GOLM1." (PMID 34680291, 2021). "The differential expression of MYO6 and GOLM1 in AA prostate cancer tissue suggests transport of RTK proteins and the resulting oncogenic activity of Akt might be a good target to treat the AA aggressive prostate cancer phenotype." (PMID 34680291, 2021). "Myosin VI (MVI) has been found to be overexpressed in ovarian, breast and prostate cancers." (PMID 29187741, 2017).
gastric cancer (12 papers, 2002 to 2025). A primary or metastatic malignant neoplasm involving the stomach. "According to reports, the excessive expression of MYO6 has been linked to a malignant characteristic in individuals diagnosed with different types of cancer, such as prostate and gastric cancer." (PMID 37965333, 2023). "Taken together, these results suggest that MYO6 is a direct target of miR-145-5p in prostate cells, as previously shown in gastric cancer and 293T kidney cells." (PMID 38673886, 2024). "A prior study revealed that concurrent overexpression of miR-145-5p and miR-143-3p, a member of the miR-145-5p family, synergistically suppressed MYO6 expression in gastric cancer, exhibiting greater inhibitory effects than miR-145-5p alone." (PMID 38673886, 2024). "The Cancer Genome Atlas (TCGA) and Genotype-Tissue Expression (GTEx) data were used to analyze UCA1 and myosin VI (MYO6) expression in gastric cancer." (PMID 34238213, 2021). "In gastric cancer, MYO6 acts as a pro-metastatic or pro-EMT gene and is directly regulated by miR-143, as well as by miR-145." (PMID 34944712, 2021). "The roles of the UCA1/miR-145/MYO6 axis in gastric cancer in vitro and in vivo were investigated by CCK-8 assay, flow cytometry, siRNAs, immunohistochemistry, and a mouse xenograft model." (PMID 34238213, 2021). "Western blot and quantitative real-time PCR (QPCR) were performed to test the expression level of the UCA1/miR-145/MYO6 axis in gastric cancer cell lines and tissues." (PMID 34238213, 2021). "MiR-143 can suppress gastric cancer cell migration and metastasis by inhibiting MYO6 and EMT; it can also regulate the proliferation and migration of osteosarcoma through MAPK7." (PMID 31976313, 2020). "Similarly, the increased expression of lncRNA UCA1 has been shown to promote the invasion and metastasis of gastric cancer cells by acting as a sponge for miR-145, thereby influencing the expression of MYO6." (PMID 40299524, 2025). "However, to our knowledge, no other reports related to galectin 3, S100A10, desmoplakin, occludin, keratins 8, 14, myosin VI, tubulin beta 4 and calveolin-3 in gastric cancer have been published." (PMID 12402156, 2002). "miR-145 mimics or MYO6 siRNAs could partly reverse the effect of UCA1 on gastric cancer cells." (PMID 34238213, 2021). "In gastric cancer, miR-145 could inhibit the tumor cell migration by targeting MYO6." (PMID 32178736, 2020). "UCA1 accelerated cell proliferation and inhibited cell apoptosis through sponging miR-145 to upregulate MYO6 expression in gastric cancer, indicating that the UCA1/miR-145/MYO6 axis may serve as a potential therapeutic target for gastric cancer." (PMID 34238213, 2021).
colorectal cancer (10 papers, 2019 to 2025). A primary or metastatic malignant neoplasm that affects the colon or rectum. "Functionally, high expression of FGFR1 has been shown to be associated with increased proliferation and invasion of colorectal cancer cells; MYO6 is known to be an oncogene in CRC, while CDK9 has been used as a potential target for the treatment of CRC." (PMID 38877540, 2024). "Downregulation of circ_0011385 in colorectal cancer inhibited cell proliferation and promoted apoptosis by regulating the miR-330-3p/MYO6 axis." (PMID 36065412, 2022). "SOX21-AS1 accelerates the tumorigenesis of colorectal cancer by affecting myosin VI (MYO6) expression." (PMID 36335356, 2022). "For instance, miR-545-3p enrichment could suppress colorectal cancer cell malignant behaviors by depleting MYO6 expression." (PMID 36612120, 2022). "Therefore, HNF1A-AS1 can influence cell migration, invasion, and glycolysis by regulating the miR-124/ MYO6 axis of colorectal cancer cells." (PMID 35003365, 2021). "So Hsa_Circ_0000231 acts on MYO6 through miR-502-5p to regulate glycolysis in colorectal cancer." (PMID 35003365, 2021).
hypertrophic cardiomyopathy (6 papers, 2017 to 2024). A condition in which the myocardium is hypertrophied without an obvious cause. "To date, an association of hypertrophic cardiomyopathy with myosin VI loss has been described for a number of patients and two different mouse models." (PMID 28096472, 2017). "Interestingly, symptoms of hypertrophic cardiomyopathy have been reported in adult patients with a point mutation within MYO6." (PMID 35837016, 2022). "Interestingly, the loss of myosin VI in mice and humans manifests as two pathologies affiliated with connexin derangements: sensorineural deafness and hypertrophic cardiomyopathy." (PMID 28096472, 2017).
autosomal dominant non-syndromic hearing loss (5 papers, 2019 to 2026). "A frameshift mutation at the N-terminus (p.Thr13fs), located in annotated exon 1 of MYO6, is associated with autosomal recessive hearing loss, DFNB37 (arrow)." (PMID 38562617, 2024). "In Case #6, we identified a novel MYO6 variant c.1939T > C, p.(Phe647Leu) in a family with late-onset autosomal dominant nonsyndromic hearing loss." (PMID 34997062, 2022). "In conclusion, our study presents a distinctive manifestation of autosomal dominant non-syndromic hearing loss (ADNSHL) in a Chinese family, underscored by the identification of novel compound heterozygous variants within the MYO6 gene." (PMID 38274113, 2023). "Members of the myosin superfamily (MYO7A, MYO15A, and MYO6) are involved in voice conduction, but variants in MYO15A are now considered to be one of the most common causes of nonsyndromic autosomal recessive hearing loss (ARNSHL)." (PMID 31250571, 2019).
cardiomyopathy (4 papers, 2017 to 2024). A disease of the heart muscle or myocardium proper. "A study suggested that MYO6 mutations in humans were also associated with cardiomyopathies." (PMID 38164514, 2023). "A fuller understanding of this derangement may explain the cardiomyopathy or gliosis associated with the loss of myosin VI." (PMID 28096472, 2017).
lung carcinoma (4 papers, 2020 to 2025). "The upregulation of MYO6 is found to be associated with maintaining the cell cycle and cell growth in lung cancer cells." (PMID 37965333, 2023). "The results of this study are consistent with previous conclusions that MYO6 expression is upregulated in NSCLC tumors and MYO6 promotes tumor migration in lung cancer." (PMID 41262242, 2025). "Knocking down MYO6 could influence cell growth and proliferation in lung cancer through the phosphorylation of ERK1/2 and the microRNA-5195-3p/MYO6 axis." (PMID 41262242, 2025). "To validate the sequencing results, we selected three genes (MUC1, MYO6, and IGKC) among the 11 important molecular marker candidates for silent transient cell line construction and transferred silent MUC1 and MYO6 into lung cancer cell line A-549, and silent IGKC into normal lung cell HPAEC." (PMID 39991571, 2025). "And the role of MYO6 in lung cancer was confirmed by experiments in vitro." (PMID 41262242, 2025). "Concluding our investigation, qRT-PCR experiments confirmed the heightened expression levels of EPHX1, LDHA, SHC1, MYO6, and TLE1 in lung cancer cell lines." (PMID 37965333, 2023).
ovarian carcinoma (4 papers, 2010 to 2025). A malignant neoplasm originating from the surface ovarian epithelium. "In ovarian carcinomas, myosin VI expression has been associated with the aggressive behaviour of the tumour." (PMID 20074327, 2010). "Furthermore, myosin VI is linked to E-cadherin and beta-catenin in ovarian cancer." (PMID 20074327, 2010). "The expression of Myo6 has been shown to be proportional to cancer aggressiveness in ovarian cancer an inhibition of Myo6 by antisense RNA decreased invasion and metastasis." (PMID 33171868, 2020). "Recently, myosin VI was found to have crucial functions in the dissemination of ovarian cancer." (PMID 27121062, 2016). "There is also evidence that links myosin VI to the migration of human ovarian cancer cell lines." (PMID 20074327, 2010).
cardiac hypertrophy (3 papers, 2016 to 2024). "Progressive sensorineural hearing loss/hypertrophic cardiomyopathy syndrome is associated with myosin VI (MYO6) mutations and is characterized by sensorineural hearing loss, prolonged QT interval, and mild cardiac hypertrophy." (PMID 39596569, 2024). "In agreement with previous studies from other cardiac hypertrophy models, we found an up-regulation of contractile proteins like actin and myosin VI." (PMID 27234427, 2016).
colon cancer (3 papers, 2021 to 2025). "Increased MYO6 expression in colon cancer is regulated by a complex interplay between microRNAs (miR) and long non-coding RNAs (lncRNA)." (PMID 33670106, 2021). "Little is known about the functional consequences of MYO6 overexpression in colon cancer cells, where it appears to have pro-growth and pro-survival activities." (PMID 33670106, 2021). "MYO6 knockdown inhibited cell proliferation, migration, and invasion and induced apoptosis in colon cancer through Circ_0011385/miR-330-3p/MYO6, the lncRNA SOX21-AS1/miR-145/MYO6, HNF1A-AS1/miR-124/MYO6, and the CircCSNK1G1/miR-455-3p/MYO6 axis." (PMID 41262242, 2025).